HERC1 (HECT and RLD domain containing E3 ubiquitin protein ligase family member 1)
Description:
Involved in membrane trafficking via some guanine nucleotide exchange factor (GEF) activity and its ability to bind clathrin. Acts as a GEF for Arf and Rab, by exchanging bound GDP for free GTP. Binds phosphatidylinositol 4,5-bisphosphate, which is required for GEF activity. May also act as a E3 ubiquitin-protein ligase which accepts ubiquitin from an E2 ubiquitin-conjugating enzyme in the form of a thioester and then directly transfers the ubiquitin to targeted substrates.
Synonyms: p532; p619; MDFPMR
Tractability: Small molecule: a structure with a bound ligand is known. Antibody: UniProt places it where antibodies can reach, with medium confidence. PROTAC: ubiquitination databases record sites on it; its protein half-life has been measured.
Gene: Protein-coding gene on chromosome 15 (63,608,618 to 63,833,948, reverse strand). Ensembl gene ENSG00000103657.
Subcellular location: Membrane; Cytoplasm, cytosol; Golgi apparatus
Pathways (Reactome):
Immune System: Antigen processing: Ubiquitination & Proteasome degradation
Gene Ontology:
Molecular function: guanyl-nucleotide exchange factor activity; ubiquitin protein ligase activity; ubiquitin-protein transferase activity
Biological process: protein ubiquitination
Cellular component: cytoplasm; Golgi apparatus; cytosol; membrane
Genetic constraint (gnomAD): Loss-of-function variants: 133 observed, 465.77 expected, observed/expected ratio (o/e) 0.29, 90% interval 0.25 to 0.33. The upper end of that interval is the gene's LOEUF score, 0.33, which puts it in group 1 of 6, group 1 being the genes least tolerant of losing a copy. Missense variants: 4,574 observed, 5,665.5 expected, observed/expected ratio (o/e) 0.81, 90% interval 0.79 to 0.83. Synonymous variants: 2,054 observed, 2,083.7 expected, observed/expected ratio (o/e) 0.99, 90% interval 0.95 to 1.02.
Homologues: Orthologues: chimpanzee HERC1 (99% identical), macaque HERC1 (99% identical), rabbit HERC1 (98% identical), dog HERC1 (98% identical), pig HERC1 (98% identical), mouse Herc1 (97% identical), rat Herc1 (97% identical), guinea pig HERC1 (91% identical), tropical clawed frog herc1 (85% identical), zebrafish herc1 (80% identical), Drosophila melanogaster Rcc1 (2% identical), Caenorhabditis elegans ran-3 (2% identical), and 1 more. Paralogues in human: ALS2 (5% identical), RCC1 (3% identical), RPGR (3% identical), RCC1L (3% identical), RCC2 (2% identical), RCBTB1 (2% identical), RCBTB2 (2% identical), RCCD1 (2% identical), SERGEF (2% identical).
Diseases named in the same sentence as HERC1 in open-access papers:
HERC1 is named in the same sentence as 68 diseases in open-access papers, as found by Europe PMC text mining. Sharing a sentence is not in itself a finding about the gene and the disease. The quoted sentences say what the papers report.
Intellectual disability (11 papers, 2018 to 2025). "The role of HERC1 in nervous system function is relatively well studied, and mutations in the HERC1 gene are associated with other pathologies, primarily intellectual disability." (PMID 39336805, 2024). "HERC1 is a ubiquitin ligase protein, which, when mutated, induces several malformations and intellectual disability in humans." (PMID 32694577, 2020). "For these reasons, it has been recommended to consider HERC1 mutations in the differential diagnosis of severe intellectual disability and behavioral problems." (PMID 30140388, 2018). "Biallelic mutations in human HERC1 have been associated with overgrowth, intellectual disability and some autistic features." (PMID 30140388, 2018). "Mutations in HERC1 have been associated with intellectual disability and autism spectrum disorders." (PMID 30361487, 2021). "Mutations in the human HERC1 E3 ubiquitin ligase protein develop intellectual disability." (PMID 33328904, 2020). "In humans, mutations of HERC1 cause a polymorphic syndrome with or without cerebellar affectation, yet always apparently associated with intellectual disability and in some cases related to the autism spectrum." (PMID 33328904, 2020). "In addition, genes involved in learning and memory (ARHGAP39 and HERC1), intellectual disability (SOBP), or autism (NF1), whose mutations cause neurodevelopmental, behavioral, learning, and motor abnormalities, are repressed by exercise and normalized or slightly induced upon subsequent rest." (PMID 40725218, 2025). "Some candidates have been linked to intellectual disability (ID), such as CRBN, GPKOW, HERC1 and KCNA4, or to other behavioral disorders, such as CDC42EP4 and SLITRK5." (PMID 30102725, 2018). "Therefore, we postulate HERC1 as an important regulator in neurodevelopment, and particularly in the alterations of synaptic transmission homeostasis, one of the bases of the intellectual disability." (PMID 32694577, 2020). "To date, only recessive mutations in HERC1 have been found as causal for intellectual disability, and no phenotype has been described for the parents harboring a single HERC1 variant, so the relevance of HERC1 missense variants for CAS cannot currently be determined." (PMID 29463886, 2019).
breast carcinoma (9 papers, 2018 to 2025). "Finally, we conducted an in silico analysis to study the association between HERC1 protein expression levels in the primary tumors and breast cancer patient’s overall survival (OS), using an online KM-Plotter database." (PMID 33804079, 2021). "HERC1 is a ubiquitin ligase, and our in vitro and in vivo experiments demonstrated that its depletion decreases invasiveness in highly aggressive breast cancer cells." (PMID 33804079, 2021). "We confirmed that its depletion reduces tumorigenicity and the appearance of metastasis foci and determined that HERC1 protein expression inversely correlates with breast cancer patients’ overall survival." (PMID 33804079, 2021). "Using this approach, we identified HERC1 as a putative positive regulator of migration in human breast cancer." (PMID 33804079, 2021). "HERC1 can modulate breast cancer cells migration and invasion." (PMID 35064108, 2022). "HERC1 was reported to mediate the metastasis of breast cancer cells." (PMID 35637966, 2022). "HERC1 used to be reported to influence the metastasis of breast cancer." (PMID 35637966, 2022). "For instance, HERC1 was indicated to modulate the migration and invasion in breast cancer cells." (PMID 35064108, 2022). "Finally, we conducted an in silico analysis using publicly available protein expression data and observed an inverse correlation between HERC1 expression levels and breast cancer patients’ overall survival." (PMID 33804079, 2021). "Moreover, an in silico analysis of HERC1 protein levels in breast cancer patients’ samples indicated that high expression in primary tumors correlates with decreased survival, compared to low-expressing tumors." (PMID 33804079, 2021). "Finally, we investigated the prognostic value of HERC1 protein expression in patients with breast cancer using the Kaplan–Meier plotter database." (PMID 33804079, 2021). "Altogether, our findings demonstrate that HERC1 might represent a novel therapeutic target for the development or improvement of breast cancer treatment." (PMID 33804079, 2021). "Altogether, our results indicate that HERC1 has great potential as a putative new target for the treatment of breast cancer and that its modulation could directly or indirectly regulate tumor cell motility and therefore patient’s outcome." (PMID 33804079, 2021). "Mutations in HERC1 were detected in leukemias, breast cancers and, more recently, HERC1 has been associated with non-melanoma skin cancer through regulation of E6-mediated BAK degradation." (PMID 30140388, 2018). "Next, we analyzed whether HERC1 KD affects breast cancer cell clonogenicity." (PMID 33804079, 2021). "Altogether, we demonstrate that HERC1 might represent a novel therapeutic target in breast cancer." (PMID 33804079, 2021). "HERC1 is the founding member of the HERC family characterized in human breast cancer cells, followed by the identification of a total of six HERC members in human, which are phylogenetically divided into large HERCs (HERC1 and HERC2) and small HERCs (HERC3-6)." (PMID 36902023, 2023). "For example, HERC1, HERC4, and HERC5 have been found to be overexpressed in human breast cancer and to promote cancer progression." (PMID 35889210, 2022). "Mutations in HERC1 and HERC2 have been detected in leukemia cells (T-cell acute lymphoblastic leukemia (T-ALL) for HERC1 and T-cell prolymphocytic leukemia (T-PLL) for HERC1 and HERC2) and in breast cancer tumors." (PMID 31275856, 2019). "However, Herc1 was recently identified as a key player of a quality-control protein that monitors failures during proteasome assembly, specifically by mean of ubiquitination of PSMC5-PAAF1 complex in the aneuploidy breast cancer cell line MCF7." (PMID 39859507, 2025). "In contrast, the role of HERC1 in the control of tumor cell invasion has not been studied yet, and therefore we decided to further investigate its potential as a novel molecular target in breast cancer." (PMID 33804079, 2021).
leukemia (6 papers, 2018 to 2021). A malignant (clonal) hematologic disorder, involving hematopoietic stem cells and characterized by the presence of primitive or atypical myeloid or lymphoid cells in the bone marrow and the blood. "Besides these reports, in which the HERC1 mutational status has been associated with different leukemia, the cellular functions of this protein in leukemia cells have been scarcely investigated." (PMID 33477751, 2021). "In addition, HERC1 point mutations were recurrently found in few leukemias such as T-ALL, AML and T-cell prolymphocytic leukemia." (PMID 33477751, 2021). "We examined the gene expression of HERC1 in this type of leukemia according to the most common cytogenetic and genetic alterations." (PMID 33477751, 2021). "When compared to the pool of PB and BM healthy specimens, the HERC1 gene expression was sharply downregulated at diagnosis both in acute (median value approximately of 1.0) and in chronic myeloid (median value approximately 0.93) leukemia." (PMID 33477751, 2021). "In addition to that, an atypical HERC1-PML transcript fusion mRNA and HERC1 mutations are also found in leukaemia." (PMID 31447701, 2019). "These include mutations in genes known to cooperate with CBF-rearrangements [e.g. NRAS (n = 6), KRAS (n = 4), FLT3 (n = 2), KIT (n = 3), ZBTB7A (n = 2)] as well as in genes, which have not been described to be mutated in CBF leukemia so far (e.g. ZFHX4, NFE2, HERC1)." (PMID 31896782, 2020).
acute lymphoblastic leukemia (4 papers, 2018 to 2022). Leukemia with an acute onset, characterized by the presence of lymphoblasts in the bone marrow and the peripheral blood.
Osteopenia (3 papers, 2023 to 2024). Osteopenia is a term to define bone density that is not normal but also not as low as osteoporosis. "In summary, this study identifies HERC1 as a regulator of bone remodeling, associates HERC1 deficiency with osteopenia, and suggests molecular targets for therapeutic strategies." (PMID 36635269, 2023). "This study provides the first evidence that HERC1 controls bone homeostasis and that loss of its function causes osteopenia." (PMID 36635269, 2023). "Taken together, these results show a correlation between female-associated osteopenia, with lower concentrations of testosterone and dihydrotestosterone, in young Herc1-KO mice." (PMID 36635269, 2023). "In a preclinical model, we also found that HERC1 loss-of-function caused osteopenia in adulthood." (PMID 36635269, 2023). "Other non-neurological diseases related to HERC1 include human immunodeficiency virus (HIV) acquisition and acquired immunodeficiency syndrome (AIDS), diabetes, cardiovascular disease and osteopenia (HERC1 section)." (PMID 36902336, 2023). "As a novelty, our study reports a greater sensitivity to developing osteopenia in young Herc1-KO female mice than in WT controls." (PMID 36635269, 2023). "The Herc1-knockout adult mice developed imbalanced bone homeostasis that presented as osteopenia in both sexes of the adult mice." (PMID 36635269, 2023). "Despite the increased gene expression of osteoblastic differentiation activators, morphometric analysis of bones from adult Herc1-KO mice showed osteopenia, indicating an imbalance between bone formation and bone resorption." (PMID 36635269, 2023). "Therefore, HERC1 is a candidate to be evaluated to identify the etiology of osteopenia." (PMID 36635269, 2023).
osteosarcoma (3 papers, 2018 to 2020). A usually aggressive malignant bone-forming mesenchymal neoplasm, predominantly affecting adolescents and young adults. "In the ubiquitin ligase HERC1-depleted cells, for example, activation of p38 increases the migration of human osteosarcoma U2OS cells." (PMID 32861245, 2020). "Human osteosarcoma U2OS cells, frequently used in cell signaling studies, were transfected with two different small interfering RNA (siRNA) of HERC1 (Q1 or Q4)." (PMID 30140388, 2018). "Human osteosarcoma U2OS cells were transfected with small interfering RNA (siRNA), using two different HERC1 siRNAs (Q1 and Q4) and a non-targeting (NT) siRNA." (PMID 31965002, 2020).
schizophrenia (3 papers, 2022 to 2025). A major psychotic disorder characterized by abnormalities in the perception or expression of reality. "High-risk variants for schizophrenia were identified in the PTVs of Grin2A, Herc1, and Trio through exome analysis." (PMID 39774335, 2025). "Research suggests that mutations in the HERC1 gene may contribute to developmental abnormalities of the nervous system and development of mental illnesses such as autism spectrum disorder, depression, and schizophrenia." (PMID 39640846, 2024). "These genes encompass high-odds risk genes of schizophrenia identified by SCHEMA, including Gria3, Grin2A, Herc1, and Trio." (PMID 39774335, 2025).
Ataxia (2 papers, 2020 to 2022). Ataxia refers to impaired coordination of voluntary muscle movement. "The tambaleante (tbl) mouse carries a HERC1 mutation characterized by cerebellar ataxia due of adult cerebellar Purkinje cells death by extensive autophagy." (PMID 33328904, 2020). "In mice, HERC1 is widely expressed with highest transcript expression in the brain, and a spontaneous missense mutation (G483E) resulted in delayed growth, short body, high juvenile mortality and severe ataxia as a result of Purkinje cell degeneration in mice." (PMID 35502705, 2022).
chronic myelogenous leukemia (2 papers, 2021 to 2022). "Our findings revealed that HERC1 gene expression was severely downregulated both in acute and in chronic myelogenous leukemia at diagnosis, while it is restored after complete remission achievement." (PMID 33477751, 2021). "Indeed, though both genes appear to be severely downregulated in chronic myeloid leukemia cells, the effect of Dasatinib on the HERC1 and HERC2 gene expression is different." (PMID 35054018, 2022).
myeloproliferative neoplasm (2 papers, 2021). A clonal hematopoietic stem cell disorder, characterized by proliferation in the bone marrow of one or more of the myeloid (i.e., granulocytic, erythroid, megakaryocytic, and mast cell) lineages. "At diagnosis, HERC1 transcript levels are markedly down-regulated in AML, CML and primary myelofibrosis, an aggressive form of myeloproliferative neoplasm (MPN), relatively to bone marrow and peripheral blood control cells." (PMID 35201500, 2021). "Instead, in Philadelphia the negative myeloproliferative neoplasm HERC1 level was peculiarly controlled, being very low in Primary Myelofibrosis and significantly upregulated in those Essential Thrombocytemia specimens harboring the mutation in the calreticulin gene." (PMID 33477751, 2021).
Parkinson disease (2 papers, 2020 to 2022). A progressive degenerative disorder of the central nervous system characterized by loss of dopamine producing neurons in the substantia nigra and the presence of Lewy bodies in the substantia nigra and locus coeruleus. "Other interesting associations reported in the GWAS catalogue include Parkinson’s disease (LZB3), educational attainment (FRZB and GLI3) and ADHD/Externalising behaviour (HERC1)." (PMID 36415660, 2022).
T-cell prolymphocytic leukemia (2 papers, 2019 to 2022). A slow-growing type of leukemia (blood cancer) in which too many lymphocytes are found in the bone marrow and/or blood. "Recurrent mutations of both HERC1 and HERC2 have also been detected in T cell prolymphocytic leukemia with a frequency of approximately 10%." (PMID 35054018, 2022).
adenoma (1 paper, 2021). A neoplasm arising from the epithelium. "Additionally, when we compared proteomic profiling of adenomas, to the proteomic expression of colon biopsies, there were some moieties (ATP5J2, DPAGT1, PTPLB, HERC1, and COX6C) that were down-regulated in both." (PMID 33799486, 2021).
Arthritis (1 paper, 2021). Inflammation of a joint. "The top-ranked genes associated with arthritis and skeletal disease in humans were Pitx1, coiled-coil domain containing 6 (Ccdc6), HECT and RLD domain containing E3 ubiquitin protein ligase family member 1 (Herc1), nebulette (Nebl), Sh3bp4, and Zfp341." (PMID 33473114, 2021).
colon cancer (1 paper, 2021). "A transcriptomic analysis carried out on a colon cancer cell line treated with ER stressors (e.g., brefeldin A and tunicamycin) revealed an up-regulation of a large group of autophagy related genes, including HERC1." (PMID 33477751, 2021).
developmental delay (1 paper, 2024). "We identified a novel loss-of-function homozygous variant (NM_003922.3:c.1280dup) in HERC1 in a proband with a spectrum of neurological and musculoskeletal manifestations including developmental delay, macrocephaly, and neurological abnormalities." (PMID 39891458, 2024).
head and neck squamous cell carcinoma (1 paper, 2026). A squamous cell carcinoma that arises from any of the following anatomic sites: lip and oral cavity, nasal cavity, paranasal sinuses, pharynx, larynx, and salivary glands. "This study identifies HERC1 as a critical regulator of cancer stemness, metastasis, and chemoresistance in head and neck squamous cell carcinoma (HNSCC)." (PMID 41965446, 2026).
lung carcinoma (1 paper, 2023). "Among these circRNAs, circHERC1 was characterized as a lung cancer-associated circRNA derived from exons 22–27 of HERC1 that was formed a circRNA through back-splicing." (PMID 37932766, 2023).
mental disorder (1 paper, 2024). A disease that has its basis in the disruption of mental process. "Interestingly, the HERC1 gene is associated with various mental disorders." (PMID 39640846, 2024).
myeloid leukemia (1 paper, 2021). A clonal proliferation of myeloid cells and their precursors in the bone marrow, peripheral blood, and spleen. "Though, in myeloid leukemia and related neoplasms, the HERC1 transcript levels were mostly down-regulated, thus likely acting as an oncosuppressor, we noticed that there are few remarkable exceptions suggesting that its role is tightly context-dependent." (PMID 33477751, 2021).
periodontitis (1 paper, 2024). An acute or chronic inflammatory process that affects the tissues that surround and support the teeth. "The TWAS indicated that five cross-trait genes, including CC2D2B (10q24.1), RP11-326C3.7 (11p15.5), USP3 (15q22.31), HERC1 (15q22.31), and AMFR (16q13), may be implicated in the interaction of circulating immune cells with periodontitis." (PMID 38536078, 2024).
tauopathy (1 paper, 2025). Neurodegenerative disorders involving deposition of abnormal tau protein isoforms (tau proteins) in neurons and glial cells in the brain. "Whether and how HERC1, PJA2, and MYCBP2 participate in tauopathy and mediate the protective effect of sorafenib requires further scrutiny." (PMID 41311387, 2025).